FABP5 (fatty acid binding protein 5)
Diseases named in the same sentence as FABP5 in open-access papers (continued):
Sharing a sentence is not in itself a finding about the gene and the disease.
cancer (continued). "FABP5, as an intracellular chaperone of fatty acids, is involved in the regulation of lipid metabolism and cell growth, and its expression is increased in various cancers." (PMID 39963593, 2025). "FABP5 has been reported to inhibit ferroptosis in cancer cells." (PMID 39928282, 2025). "Although PPARβ/δ has been implicated in FABP5-mediated oncogenic signalling in other cancers, its role appears to be non-essential in CRC, with FABP5-driven progression occurring through alternative pathways." (PMID 41149452, 2025). "FABP5 demonstrates significant prognostic value and therapeutic potential across multiple cancers." (PMID 40717587, 2025). "In addition, exploring the functional significance of USP14 and FABP5 in various cancer types will enhance our overall comprehension of their functions in cancer biology on a broad scale." (PMID 39928282, 2025). "Similarly, silencing fatty acid-binding protein 5 (FABP5) in increases LDs levels in cancer cell lines, inhibiting NF-κB activation." (PMID 40566856, 2025). "Indeed, a substantial body of research supports the oncogenic role of FABP5 in different types of cancer." (PMID 39928282, 2025). "FABP5 is essential in the progression of cancer and metabolic diseases." (PMID 39871325, 2025). "In addition, it was shown that FABP5 was also identified as a pivotal factor regulating the pathogenesis of various malignant tumors." (PMID 40429934, 2025). "Prkca contributes to protection against LPS-induced inflammation in RAW264.7 macrophages as well as ROS production in cancer cell-lines, suggesting that FABP5 may modulate ROS levels in macrophages." (PMID 37790380, 2023). "Consistent with these in vitro findings, CD8+ T cells isolated from the ascites of HGSOC patients demonstrated a significant reduction in surface FABP5 expression compared with peripheral CD8+ T cells from cancer-free women, although their total FABP5 levels were comparable." (PMID 38168227, 2023). "Actually, a lot of studies have proved that FABP5 has a promoting effect in many cancers." (PMID 36792587, 2023). "Therefore, we conducted a pan-cancer analysis of FABP5 based on the data from TCGA and GTEx database." (PMID 36906605, 2023). "Interestingly, consistent with the dual role of ALKBH5 played in tumors, FABP5 seems also function contradictory effect in different cancers." (PMID 37858219, 2023). "Most extensively examined has been the role of FABP5 in numerous types of cancer." (PMID 37207357, 2023). "KLF2 affects the proliferative ability of cancer cells by modulating the FABP5/PPARγ axis." (PMID 37256177, 2023). "FABP5 is sought to supply ligands for PPARβ/δ and mediate the cancer progression." (PMID 37256177, 2023). "In addition, fatty acid metabolism regulated by FABP5 has been also confirmed to play crucial roles in the progression of many cancers." (PMID 36792587, 2023). "Taken together, our study made a pan-cancer analysis of FABP5 on the basis of the clinical data from The Cancer Genome Atlas (TCGA) database for the first time, and observed novel FABP5-related regulatory networks in kidney renal clear cell carcinoma (KIRC) and liver hepatocellular carcinoma (LIHC)." (PMID 36906605, 2023). "Therefore, FABP5 gene is not only closely related to diverse cancer types, but also has been widely reported in the field of livestock and poultry molecular breeding research." (PMID 36952432, 2023). "Moreover, FABP4 and FABP5—known to be regularly expressed during adipocyte differentiation—have been found at high levels in cancers of the prostate, breast, and ovaries, where they promote malignant progression and metastasis and worsen prognosis." (PMID 36497485, 2022). "FABP5 is involved in the malignant dissemination of some human cancers." (PMID 35445019, 2022).
cancer (continued). "In contrast, miR-21 increased intracellular phospholipids and TG, and enhanced gene expression of key enzymes in lipogenesis, such as fatty acid synthase (Fasn), acetyl-CoA carboxylase (Acaca), and fatty-acid binding protein 5 (Fabp5) in A549 cells or H1703 cancer cells." (PMID 36360201, 2022). "The roles and mechanisms of FABP5 in various types of cancer." (PMID 35445019, 2022). "It was reported that FABP5 may regulate the development and progression of cancer cells by mediating signaling pathways that are involved in EMT." (PMID 35445019, 2022). "Nuclear translocation of FABP4 and FABP5 proteins mediated by lipid ligands, including EETs, can activate transcription factors (TFs) to initiate proliferative or cell death signaling in several cancer models." (PMID 31941087, 2020). "In MMTV-ErbB2/HER2 onco-mice, knockout of FABP5, which shuttles ligands from the cytosol to nuclear PPARβ/δ was sufficient to reduce mammary tumorigenesis highlighting the importance of this molecule and endogenous PPARβ/δ ligands for cancer growth." (PMID 32375405, 2020). "Given that the important role of FA metabolism in cancer metastasis has been highlighted, we speculated that FABP5 promotes LNM in CCa by reprogramming FA metabolism." (PMID 32550890, 2020). "Moreover, they suppressed the expression of the cancer-promoting gene, fatty acid-binding protein 5 (FABP5)." (PMID 31687492, 2019). "FABP5 is involved in intracellular fatty acid transport, and thus its depletion in PCa cells might lead to remodeling cancer metabolism." (PMID 30167092, 2018). "Previous studies suggested that FABP5 regulates the signaling activities of peroxisome proliferator-activated receptor β/δ (PPARβ/δ), a ligand-dependent transcription factor, by functioning as a free fatty-acid transporter in various cancer cells." (PMID 30167092, 2018). "However, the molecular mechanisms of FABP5 in cancer cell proliferation and its other functions have remained unclear." (PMID 30167092, 2018). "The closer to adipose tissue the cancer, the higher expression of FABP5." (PMID 29914512, 2018). "Further mechanistic studies are required to better understand FABP5 functions in cancer cells." (PMID 30167092, 2018). "Previous studies showed that FABP5 promotes cell proliferation of cancer cells." (PMID 30167092, 2018). "One study after another has reported that FABP5 could transport large amounts of intracellular FAs into nucleus to activate PPARs, which may then activate downstream cancer-promoting genes." (PMID 29914512, 2018). "It is, therefore, proposed that the ratio of CRABP2 and FABP5 and the status of expression of their corresponding nuclear receptors may determine RA sensitivities of cancer cells." (PMID 29596381, 2018). "However, we have preliminarily found that EGCG has less inhibitory activity for the cancer-promoting gene (FABP5) expression and less invasive activity compared with these epicatechin oligomers (unpublished results)." (PMID 28798415, 2017). "We next performed a human cancer pathway finder PCR array, using HepG2‐FABP5 and HepG2 control cells to examine the hypothesis that FABP5 affects the expression of genes that contribute to HCC aggressiveness." (PMID 28374947, 2017). "Furthermore, these epicatechin oligomers suppressed significantly the expression of the cancer-promoting gene, FABP5, which is related to cell proliferation and metastasis in various cancer cells." (PMID 28798415, 2017). "Taken together, FABP5, within the cancer cell, is necessary for metastatic potential of TNBC cells." (PMID 25779666, 2015). "Because the biological consequences of these two pathways are distinct, the expression levels of CRABP-II and FABP5 may determine the RA sensitivities and outcome of cancer cells treated with RA." (PMID 25797252, 2015). "In non-cancer keratinocytes FABP5 elevation may be necessary for the activation of cell motility during epidermal wound healing." (PMID 22673103, 2012).
cancer (continued). "Interestingly, several of these small and large altered regions contain cancer-associated genes known to be involved in CRC and/or the metastatic process: i.e. the TPD52, FABP5, MAP2K4, LLGL1, FBLN1 and TYMP genes." (PMID 21060790, 2010). "FABP5 was detected in the sera of HNSCC patients with early stage cancer." (PMID 19602232, 2009). "Additionally, it is reported recently that FABP5 can inhibit ferroptosis in cancers." (PMID 39928282, 2025). "FABP5, an intracellular companion of fatty acid molecules that regulates lipid metabolism and cell growth, has been found to be abundantly expressed in different cancer types and involved in a variety of biological processes such as proliferation, differentiation, migration, and invasion." (PMID 39194582, 2024). "This indicates that an elevated expression of FABP5 may induce metastasis of cancer cells." (PMID 35445019, 2022). "In addition, silencing FABP5 may reduce the invasiveness of cancer cells, inhibit cell proliferation, and increase cell apoptosis." (PMID 35445019, 2022). "In addition to the role of FABP5 in metabolic diseases, FABP5 may also play a critical role in cancer progression." (PMID 33128030, 2020). "Moreover, recent studies have shown that FABP5 participates in cancer progression 16-24." (PMID 32550890, 2020). "Ablation of FABP5 probably affects TG storage in cancer cells since FA afflux may be hindered." (PMID 29914512, 2018). "Thus, as the molecular mechanisms underlying the connection between high expression of FABP5 and cancer cell proliferation remains unclear, we searched for a novel crosstalk signaling with FABP5 in PCa cells." (PMID 30167092, 2018). "An imbalanced ratio of CRABP-II and FABP5 may determine RA sensitivities of cancer cells." (PMID 25797252, 2015). "By improving the absorption of curcumin and cellular uptake of curcumin, curcumin derivatives may be more potent in suppressing the FABP5/PPARβ/δ pathway, and enhance the efficacy of RA by reducing the dosage to be used in vivo, in order to better tolerate its use in cancer patients." (PMID 25260874, 2014). "FABP5 and its cognate receptor PPARβ/δ thus appear to function as oncogenes, and it has been suggested that inhibition of their transcriptional activities may comprise a novel strategy for treatment of some cancers." (PMID 20847935, 2010). "In pan-cancer analyses, FABP8 forms a gene cluster with FABP4, FABP5, FABP9, and FABP12, which frequently undergo co-amplification in various cancers." (PMID 40717587, 2025). "Overall, these data show that in the interaction between HCC cancer cells and TAM, the expression of FABPs, particularly FABP5, and the exchange of lipid metabolites like long-chain unsaturated FAs, reprogram TAMs via the FABP/PPAR pathway." (PMID 40507339, 2025). "The expression of the TGF-β-regulated genes (DHCR7, FABP5, HMGCR, MVD, SQLE and STARD4) was further correlated with clinical features using cancer patient datasets." (PMID 39910665, 2025). "FABP5 inhibitors (e.g., SBFI-26) show significant antitumor effects in multiple cancer models, suggesting their potential as novel therapeutic agents." (PMID 40717587, 2025). "Expression of MMP2 and MMP9 is regulated by fatty acid-binding protein 5 (FABP5), a cancer metastasis promoting protein." (PMID 38215076, 2024). "Among members of the FABP family, E-FABP (Epidermal-FABP/FABP5/keratinocyte-FABP) has been reported to be upregulated in some cancers (prostate, breast) and to participate in cancer progression." (PMID 38965292, 2024). "The 10-biomarker signature in this category additionally incorporating FABP5, C1RL, MMP9, ECM1, S100A7 and CF1, discriminated early-stage cancers from controls with an AUC of 0.92 (0.86–0.97)." (PMID 36807337, 2023). "Here we combine analysis of primary cancer cells from RapidCaP (RCaP cells) with large-scale patient datasets to show that among the 10 FABP paralogs, FABP5 is the PC-relevant target." (PMID 38201488, 2023).
cancer (continued). "Although CD36, SREBPs, PD-L1/2, FABP5, CPT-1, ACC1, GLUT1, and FAS has shown promising prospects to be potential metabolic drug targets of cancer, their context-dependence and varied implications in T-cell subtypes urge for more research." (PMID 36203151, 2022). "Next, we evaluated the effect of FABP5 on the tube formation of HLECs, which is crucial for LNM in cancer." (PMID 32550890, 2020). "The silence of FABP5 gene made effects on the proliferation, apoptosis and invasion of human gastric SGC-7901 cancer cells." (PMID 32579175, 2020). "Except for FABP5, mRNA levels of FABP12, FABP4, FABP9 and FABP8 were upregulated in cancers with higher Gleason scores." (PMID 33352874, 2020). "Compound 1 also exhibited significantly higher anti-cancer activities than EGCG through suppression of cell growth, the expression of the metastasis-promoting gene FABP5 and invasion of cancer cells." (PMID 31427660, 2019). "The migration and invasion abilities of cancer cells were significantly enhanced after co-culture with adipocytes, accompanied by elevated lipolysis and expression of ATGL and FABP5." (PMID 29914512, 2018). "According to the findings from other types of cancers, the cells with high CRABP-II expression tend to be sensitive to RA treatment and cells with high FABP5 expression tend to be insensitive to RA treatment." (PMID 25797252, 2015). "Here we showed that including FABP5 and KCNH8 as prognostic biomarkers improves aggressive cancer detection." (PMID 22811706, 2012). "Notably, genes like fatty acid binding protein 5 (FABP5), enolase 1 (ENO1), phosphoglycerate kinase 1 (PGK1), and marker of proliferation Ki-67 (MKI67), which have been extensively studied in cancer biology, were included." (PMID 41328179, 2026). "Fatty acid binding protein 5 (FABP5) mRNA is m6A‐modified, but upregulation of ALKBH5 increases FABP5 expression by decreasing m6A modification, inducing fatty acid synthesis via PI3K/AKT/mTOR signaling pathway and promoting cancer growth." (PMID 40448344, 2025). "In the case of HNC, there is notable upregulation of epidermal FABP (E-FABP, also known as FABP5), which might contribute to cancer proliferation and invasiveness." (PMID 37927468, 2023). "The anti-cancer effects of ALKBH5 (including suppression of cell proliferation, migration and invasion) were partly restored by silencing of FABP5 which indicated FABP5 could be downstream gene of ALKBH5." (PMID 37416772, 2023). "Studies show that upregulation of FABP5 can activate peroxisome proliferator-activated receptor-β/δ (PPARβ/δ) and increase FABP5 methylation levels in CPG islands to accelerate the proliferation of cancer cells." (PMID 35790992, 2022). "Nevertheless, there was no notable difference in the expression of FABP5 between cancer tissues with lower Gleason scores (scores of 1–5) and those with higher Gleason scores (scores of 5–10)." (PMID 35445019, 2022). "CXCL8 and LAPTM5 proteins have been reported to promote cell activity, TMEM156 and LGALS1 proteins enhance cell invasion, VIM and LGALS1 proteins induce cell migration, FABP5 and SRGN proteins activate cancer metastasis, and the DEFB4A protein regulates immunity in human cancers." (PMID 35632763, 2022). "FABP5 was demonstrated to promote angiogenesis through activating the IL6/STAT3/VEGFA pathway in HCC, or transporting excessive levels of fatty acids into the nucleus of the cancer cells to activate PPARγ thereby up-regulating the expression of VEGF." (PMID 35445019, 2022). "Additionally, our results indicated the OA/FABP5/HIF-1α axis facilitated HCC cell proliferation, indicating this axis is a promising therapeutic target for reversing cancer-related lipid metabolism reprogramming." (PMID 33128030, 2020). "For instance, FABP5 might be involved in MAGL-dependent signaling to regulate a FA network that promotes migration, invasion, and survival of cancer cells." (PMID 29914512, 2018).
cancer (continued). "Among these candidate markers, fatty acid binding protein 5 (FABP5) was higher in the cancer group than in the negative group (p-value = 0.009) and was significantly associated with GS (p-value for trend = 0.011)." (PMID 28211531, 2017). "However, some studies indicate that the pro‐oncogenic mechanisms of FABP5 may function independently of the PPAR β/δ or PPAR γ signaling pathways, instead relying on the modulation of fatty acid metabolism within cancer cells." (PMID 40178066, 2025). "However, there is no study analyzing the potential roles of FABP5 based on a pan-cancer perspective." (PMID 36906605, 2023). "Therefore, FABP5, as immunometabolic marker, has the potential to apply to multiple cancer types although we have no data regarding the clinical relevance of FABP5+ cells in NSCLC." (PMID 32611686, 2020). "In conclusion, the novel FABP5 inhibitor dmrFABP5 suppresses the malignant progression of CRPC by blocking fatty acid-stimulation of PPARγ and thereby it curtails its up- or down-regulating effect on the down-stream cancer-promoting or -suppressing genes in the nude mouse model of CRPC." (PMID 31258834, 2019). "Although the molecular mechanism involved in cancer-promoting activity of FABP5 has been extensively studied, it was not clear whether the CRPC can be treated by suppressing the biological activity of the oncogenic FABP5." (PMID 28415688, 2017). "Thus, a direct relationship exists between the high expression level of FABP5 and the lack of sensitivity to retinoic acid, and not the aggressiveness of the cancer." (PMID 25260874, 2014). "Interestingly, all cancer types within the DepMap database had negative FABP5 CERES values." (PMID 36880649, 2023). "Thus, TG content was detected and the results support the conclusion that FABP5 was more likely to participate in intracellular FA trafficking rather than transmembrane transportation, since down-regulation of FABP5 did not reduce lipid accumulation in cancer cells during co-culture." (PMID 29914512, 2018). "However, this does not address whether FABP5 in the cancer cell, the environment, or both is the contributing factor for worse prognosis in patient data." (PMID 25779666, 2015). "In our study, we verified that FABP5 level did not interfere with ATRA sensitivity in MPNST, like in other human cancers." (PMID 29131833, 2017). "We observed significantly higher expression of the genes related to lipid uptake and transport (FABP5 and FATP4) in African American patients irrespective of cancer subtype, while the expression of genes for lipid synthesis was lower in African American than Caucasian American." (PMID 36517516, 2022). "Based on this alternative hypothesis, disrupting the FABP5-PPARγ-VEGF signalling axis and cutting off the alternative energy supply of the cancer cells, rather than blocking the last drop of androgen, should be the correct way to kill the AR-negative CRPC cells." (PMID 26814431, 2016).
metabolic disease (14 papers, 2008 to 2026). A congenital disorder (due to inherited enzyme abnormality) or acquired (due to failure of a metabolically important organ) disorder resulting from an abnormal metabolic process. "FABP5 played an important role in the transportation and metabolism of fatty acids in various diseases including metabolism disorders." (PMID 39770043, 2024). "The finding also provided strong support for FABP5’s function in the prevention and treatment of metabolic diseases." (PMID 35445019, 2022). "FABP4 (also known as aP2/ALBP/A-FABP) and FABP5 (also referred to as mal1/E-FABP) play important roles in the pathogenesis of metabolic diseases." (PMID 24244493, 2013). "A further investigation of the mechanism of integrated actions of FABP4 and FABP5 may enable the development of new therapeutic strategies for metabolic disease and atherosclerotic cardiovascular disease." (PMID 33071982, 2020). "Furthermore, macrophage FABP5 has also been shown to be important in metabolic disease where FABP5 in the macrophage and the adipocyte play an important role in inflammatory signaling." (PMID 25779666, 2015).